BRAF (B-Raf proto-oncogene, serine/threonine kinase)
Diseases named in the same sentence as BRAF in open-access papers (continued):
Sharing a sentence is not in itself a finding about the gene and the disease.
melanoma (continued). "This suggests that BRAF V600 driven melanomas are associated with a reduced benefit from anti‐PD1 monotherapy in the advanced setting, whereas with the addition of Ipilimumab similar PFS rates are observed." (PMID 41342263, 2025). "The most common and well-known BRAF mutation is V600E, which has been detected in various cancers, such as malignant melanoma, papillary thyroid cancer, and colorectal cancer." (PMID 40959083, 2025). "Mutation profiling revealed frequent alterations in TTN (72%), MUC16 (67%), BRAF (51%), and other melanoma-associated genes." (PMID 41150769, 2025). "Taken together, our study results show that serum LDH predicts long-term survival of stage IV melanoma patients independently of treatment type and BRAF mutation status." (PMID 40028330, 2025). "Activating mutations in BRAF, particularly the V600E mutation, are found in approximately 50% of melanomas." (PMID 40507265, 2025). "Genetically, 40–50% of all melanoma patients harbor an activating BRAF mutation, mostly BRAF V600E, but there is little information on AMM." (PMID 40320509, 2025). "Early research focused on BRAF mutations, malignant melanoma, and activation, emphasizing foundational studies on molecular pathways and therapeutic targets." (PMID 39897423, 2025). "Given the low prevalence of BRAF mutations, treatment options for advanced melanoma in Japan are limited, necessitating reliance on ICIs." (PMID 40192945, 2025). "In melanoma with BRAF mutations, resistance to targeted therapy, including dual treatment with MAPK and PI3K/AKT inhibitors, is a common challenge despite early efficacy." (PMID 41008880, 2025). "The surgical pathology showed malignant melanoma that was B-Raf proto-oncogene serine/threonine kinase (BRAF)-positive with a V600E mutation." (PMID 41280706, 2025). "These include unresectable/metastatic BRAF-mutated melanoma, metastatic non-small cell lung cancer, BRAF V600E-mutated anaplastic thyroid carcinoma, and pediatric recurrent low-grade gliomas with V600 mutations." (PMID 41019984, 2025). "For BRAF-mutated melanoma, all the options available for BRAF-WT melanoma are still valid, with the addition of combined BRAFi–MEKi therapy if not already used as the immediate prior treatment." (PMID 39550033, 2025). "BRAF gene mutations in human melanoma result in an activated oncogene that constitutively activates a pro-proliferation pathway for melanocytes that promotes oncogenesis in more than half of all human melanomas." (PMID 41012800, 2025). "For melanomas with mutations outside of BRAF, targeted therapies offer promise, especially in second-line settings." (PMID 40861441, 2025). "BRAF/MEK inhibition remains a cornerstone of targeted therapy for BRAF-mutated melanoma and continues to play a key role in frontline treatment." (PMID 40564107, 2025). "In melanoma, the discovery of activating mutations in the BRAF gene (V600E/K) has transformed treatment." (PMID 41228293, 2025). "Testing for mutations involving codon 600 of the BRAF gene is necessary to establish therapeutic decisions in patients with stage 3 and 4 melanoma." (PMID 40614549, 2025). "This phenomenon has been observed in several melanoma cell lines with the BRAF V600E mutation, where loss of PTEN significantly reduces the efficacy of PLX4720." (PMID 40872623, 2025). "KIT mutations tend to occur in acral, mucosal, and CSD melanomas in older patients, and are often mutually exclusive of BRAF and NRAS mutations." (PMID 41301010, 2025). "In vemurafenib-resistant non BRAF-mutated melanoma cells, sorafenib increased intracellular ROS levels and induced ferroptosis, thereby enhancing the sensitivity of resistant tumors to vemurafenib." (PMID 40497999, 2025). "The BRAF V600E somatic mutation, discovered in 50% of melanomas, has contributed to the development of molecular targeted therapy for melanomas." (PMID 40063190, 2025). "Melanomas with BRAF mutations associated with high TMB are likely to benefit from adjuvant anti-PD-1 therapy." (PMID 39941847, 2025).
melanoma (continued). "In particular, NRAS gene mutations occur in 20–30% of melanomas and rarely coexist with BRAF V600E, appearing together in 1% of cases only." (PMID 40868208, 2025). "Mutations in NRAS or BRAF genes were observed in 80% of melanoma or melanocytic nevus cases, confirming the critical role of the MAPK pathway." (PMID 40932870, 2025). "Our results support previous findings that BRAF-mutated melanomas display a more aggressive phenotype than BRAF wild-type melanomas." (PMID 40419744, 2025). "For example, roughly 50% of melanomas are characterized by activating BRAF mutations, the most common of which is the V600E mutation, accounting for 70–88% of all BRAF mutations." (PMID 40725022, 2025). "The BRAF V600E mutation has been identified in multiple tumors, including melanoma, pleomorphic xanthoastrocytoma (PXA), ganglioglioma and papillary craniopharyngioma." (PMID 39976897, 2025). "This is consistent with previous findings for BRAFi in BRAF‐mutated melanoma, where MAPK signaling can directly activate glycolysis." (PMID 41199020, 2025). "The molecular landscape of melanoma is characterized by a diverse array of genetic alterations, including mutations in the BRAF gene present in about 50% of melanomas." (PMID 40223207, 2025). "This pathogenic BRAF V600E mutation is an oncogenic driver in many melanomas, colon, thyroid and NSCLC cancers and is a drug target for BRAF inhibitors including vemurafenib, dabrafenib and encorafenib." (PMID 40869231, 2025). "Pathogenic BRAF mutations drive constitutive MAPK pathway activation in melanoma, and targeted therapies with dabrafenib plus trametinib have improved outcomes in the adjuvant setting." (PMID 40366077, 2025). "The BRAF V600E mutation, in particular, is one of the most frequently identified genetic alterations in melanoma and is a key target for targeted therapies." (PMID 40861441, 2025). "In BRAF-mutant melanomas, loss of the CDKN2A gene is typical, but amplification of MITF and CD274 (coding for PD-L1; programmed death ligand 1) is relatively common." (PMID 40361349, 2025). "Our study included 172 patients, of which 50% were male, and 32.6% (n = 56) had BRAF-mutated melanoma." (PMID 40027067, 2025). "BRAF mutations were more frequent in younger patients, correlated with the superficial spreading melanoma subtype, and exhibited higher mitotic activity." (PMID 40332392, 2025). "Recent large-scale genomic studies in melanoma have primarily focused on mutation profiles predictive of response to treatments such as BRAF, NRAS, and CKIT inhibitors." (PMID 40004220, 2025). "Vemurafenib (VEM) is an important targeted drug for treating melanoma harboring BRAF-V600E mutation." (PMID 41145465, 2025). "EMA marketing authorisation applies to BRAF V600-mutated advanced melanoma, non-small cell lung cancer (NSCLC), low-grade glioma, and BTC in selected countries." (PMID 40093395, 2025). "The objective of this study was to evaluate the impact of two autophagy modulators, TRE and hydroxychloroquine (HCQ), on the efficacy of BRAF(V600E)-siRNA in A375 melanoma cells containing the BRAF(V600E) mutation." (PMID 41170188, 2025). "This was demonstrated by a Phase III clinical trial in patients with advanced BRAF V600E-mutated melanoma, based on the investigation of the safety and efficacy of combination therapy with BRAF and a MEK inhibitors." (PMID 41369373, 2025). "Keywords such as immunotherapy, BRAF mutations, pathway, malignant melanoma, RAF inhibition, and immune checkpoint inhibitors have emerged as central themes in the field." (PMID 39897423, 2025). "The V600E substitution in BRAF is the most common somatic mutation in melanoma, and vemurafenib was the first BRAF inhibitor approved for the treatment of late-stage BRAF V600E-positive malignant melanoma." (PMID 40040723, 2025).
melanoma (continued). "Mutations in the BRAF human proto-oncogene have been identified in 50% of malignant melanomas, and approximately 40–70% of cases show a missense mutation, with a substitution of valine with glutamic acid at codon 600, denoted as V600E." (PMID 40244045, 2025). "In melanomas harboring the BRAF V600E/K mutation, the combined use of the BRAF inhibitor PLX4720 and the MEK inhibitor PD0325901 promotes GSDM-E cleavage and the release of HMGB1, along with an upregulation of IL-1β and IL-18, leading to pyroptosis induction." (PMID 40149884, 2025). "Research conducted by Acquaviva and collaborators demonstrated that heat shock protein 90 (Hsp90) inhibition by ganetespib in BRAFV600E-mutant melanoma cell lines leads to the loss of mutant BRAF expression and a reduction in both MAPK and PI3K/AKT signaling." (PMID 40872623, 2025). "BRAF mutations are most commonly associated with superficial spreading melanoma and tumors located on the trunk, whereas NRAS mutations correlate with nodular melanoma and extremity localization." (PMID 41007741, 2025). "Understanding the oncogenic role of BRAF mutations in melanoma is crucial for the development of effective therapeutic approaches and personalized medicine." (PMID 41315179, 2025). "A retrospective analysis using our internal cBioPortal database from April 2019 to October 2023 showed that of 200 melanoma samples, a BRAF V600E mutation was identified in 33 (17%) samples." (PMID 40869231, 2025). "The immune profile of the tumor is also influenced by the BRAF mutation and its pathway, a key target in melanoma immunotherapy." (PMID 40251644, 2025). "The DREAMseq trial was a phase III trial that aimed to assess the best sequence of systemic therapy in a cohort of treatment‐naïve patients with a BRAF mutation diagnosed with unresectable melanoma." (PMID 41342263, 2025). "Patients with BRAF-mutated melanomas also demonstrate positive initial responses to BRAF/MEK inhibition therapies which offer considerable benefits." (PMID 40331942, 2025). "The researchers also found that PPARα was up-regulated and FAO was enhanced in BRAF-mutated melanoma cells after MAPK inhibition therapy, leading to cancer cell resistance." (PMID 40514365, 2025). "In mouse melanoma models, key driver mutations such as BRAF alterations and changes in genes like MET or CDKNA2 (either gain or loss) are observed to occur within lymph nodes." (PMID 40076927, 2025). "In melanoma, young patients had more frequent BRAF mutation, and complete response rates to immune checkpoint inhibitors and toxicity profiles differed from average‐aged patients." (PMID 39887374, 2025). "Preclinical models also revealed in male mice that anti-tumor responses diminished to BRAF/MEKi, associated with elevated androgen receptor (AR) expression in tumors, which promotes melanoma cell proliferation, particularly in testosterone-rich environments." (PMID 40361336, 2025). "Numerous studies have demonstrated that siRNA targeting the BRAF gene can selectively silence melanoma cell lines expressing this mutation, both in vitro and in vivo." (PMID 41170188, 2025). "Assessment of BRAF mutational status is now a standard component of the diagnostic workup for advanced melanoma." (PMID 40981345, 2025). "Melanotic melanoma cells often retain functional melanogenesis pathways and carry mutations commonly found in cutaneous melanoma, such as BRAF V600E, NRAS or NF1." (PMID 40649764, 2025). "Immunotherapy (e.g., ipilimumab, nivolumab, pembrolizumab) and target therapy (e.g., vemurafenib/cobimetinib, dabrafenib/trametinib in case of BRAF mutation) have increased the progression-free and overall survival in melanoma patients." (PMID 40278650, 2025). "The pivotal COMBI‐AD trial demonstrated the efficacy of 12 months of adjuvant dabrafenib plus trametinib (BRAF/MEK inhibitors) compared to placebo in patients with resected Stage III melanoma harboring BRAF V600E/K mutations." (PMID 40366077, 2025).
melanoma (continued). "In BRAF-mutant melanoma, tolerance to BRAFi and MEKi is closely linked to specific phenotypic plasticity, involving shifts in melanoma differentiation states and global changes in gene expression profiles." (PMID 40872623, 2025). "We demonstrated that BRAF V600-mutated melanomas exhibit biological heterogeneity, where an oncogene-induced senescence-like phenotype is associated with improved survival." (PMID 40075679, 2025). "Although BRAF inhibitors inhibit the MEK/ERK pathway in melanoma with the BRAFV600E mutation, it has been reported that a paradoxical activation of the MAPK pathway in BRAF wild‐type cells is linked to the adverse actions of vemurafenib." (PMID 40817681, 2025). "The impact of combined MEK1/2 and p110β inhibition was most pronounced in the WM266.4 line and ineffective in a further panel of additional human melanoma lines carrying BRAF and PTEN mutations, namely UACC62, SKMEL28, and WM793." (PMID 39636745, 2025). "Irregular peripheral streaks, which include pseudopods and radial projections, were observed more frequently in melanomas with BRAF mutations." (PMID 41010758, 2025). "Recurrent BRAF or NRAS mutations in melanoma activate the MAPK pathway, triggering activated ERK signaling, leading to an aggressive tumor profile with enhanced cell proliferation and survival." (PMID 39795195, 2025). "BRAF V600 mutation-targeted therapies with Dabrafenib, have be accepted as a standalone treatment for advanced melanoma with this mutation." (PMID 40066453, 2025). "The prevalence of BRAF mutations in NSCLC patients is notably lower (approximately 1–5%) compared to malignant melanoma, with almost half of these patients presenting the BRAF V600E mutation." (PMID 41480531, 2025). "Survival outcomes for TWT melanoma patients tend to be poorer compared to those with BRAF mutations." (PMID 40867277, 2025). "Among the most commonly observed mutations is in the BRAF oncogene, found in approximately 50% of melanoma cases." (PMID 40861441, 2025). "In contract, the adoption of ddPCR for detecting common melanoma mutations including BRAF, NRAS, KIT, and TERT significantly improved sensitivity, allowing ctDNA to be distinguished from total cfDNA in approximately 80% of melanoma patients." (PMID 39859576, 2025). "For melanomas with known mutation subtype following molecular BRAF testing, 74% (n = 2099/2821) were V600E." (PMID 40902091, 2025). "Considering that NRAS mutations are frequently reported as resistance mechanisms in BRAF-mutated melanomas treated with BRAF inhibitors, we investigated the effects of vemurafenib on melanoma cells harboring the NRASQ61R mutation." (PMID 40141318, 2025). "Further history revealed the patient's documented BRAF V600E mutated malignant melanoma originating from the left thigh, with biopsy‐proven lymph node metastasis to the neck." (PMID 39625060, 2025). "An activating mutation in BRAF occurs in over 50% of malignant melanomas, most of which are BRAF V600E." (PMID 40869231, 2025). "The prevalence of the BRAF gene mutation is highest in advanced melanoma, where it is found in 50–60% of patients and in 30% of localized melanomas." (PMID 39859576, 2025). "While BRAF V600E mutations are classically associated with acquired nevi and melanoma, mutations in NRAS, particularly affecting the NRAS/MAPK pathway, are frequently detected in CMN." (PMID 40265343, 2025). "Accordingly, it has been recently shown that NRAS-mutated melanomas have lower PRDX2 (peroxiredoxin 2) expression compared to BRAF-mutated melanomas, which is correlated with lower survival and higher malignancy in patients." (PMID 40141318, 2025). "Mutations common in melanoma, including BRAF, NRAS, and NF1 activate downstream signaling via the mitogen-activated protein kinase (MAPK) pathway and are more commonly found in non-ALM." (PMID 39941835, 2025).
melanoma (continued). "Acral and mucosal melanomas, although less frequently harboring BRAF V600 mutations, can also respond to these inhibitors when such mutations are present." (PMID 41302945, 2025). "Melanomas harbouring BRAF V600E mutations tend to develop in younger patients, compared to the BRAF wild-type." (PMID 40507250, 2025). "About half of melanoma patients harbor BRAF mutations and are treated with BRAF/MEK inhibitors (BRAFi/MEKi)." (PMID 41294692, 2025). "At the same time, pseudopods and radial projections were more frequently found only in BRAF-mutated melanomas." (PMID 41010758, 2025). "A similar phenomenon is observed in BRAF-mutant melanoma, where co-occurring PTEN loss or NRAS mutations activate alternative signaling pathways, ultimately limiting the efficacy of BRAF inhibitors." (PMID 40076838, 2025). "Superficial spreading melanoma is the most common form, especially in fair-skinned populations, and typically arises in intermittently sun-exposed areas, often harboring BRAF V600E mutations." (PMID 41011113, 2025). "Melanoma cells derived from two PDXs harboring NRAS (MM13) or BRAF (MM27) mutations were engineered to express H2B-GFP via lentiviral transduction." (PMID 40528051, 2025). "The data of this investigation correlate with a study from 2023 in which the authors observed that patients with BRAF–mutated melanoma had a low mutational burden in tumor tissue from brain metastases." (PMID 40028330, 2025). "Five-year net survival is lower in patients with BRAF mutations, particularly in those with stage II melanoma, emphasizing the importance of integrating BRAF testing into early-stage melanoma management." (PMID 40902091, 2025). "Collectively, the data indicated that TRIM63 interacts with ERK1/2 and undergoes phosphorylation by ERK1/2 within melanoma cells harboring BRAF mutations." (PMID 41315179, 2025). "Specific tyrosine kinase inhibitors (TKIs), including vemurafenib (V), dabrafenib (D) and encorafenib (E), have been developed to target melanoma with BRAF V600 mutations." (PMID 40507236, 2025). "Vemurafenib is the first oral drug approved for treating metastatic melanoma with BRAF V600E mutations and a significant treatment for advanced melanoma." (PMID 40861456, 2025). "Phenformin remarkably delays the development of resistance to BRAF inhibitor PLX4720 in BRAF-mutated melanoma cells." (PMID 40612109, 2025). "At low concentrations, HiGom is more potent than AgGom in diminishing the viability of BRAF-mutated melanoma cells, and with minimal impact on healthy cells at effective doses." (PMID 41271646, 2025). "Approximately 60% of melanomas contain BRAF proto-oncogene mutations, with the most common being the valine-to-glutamic acid substitution at codon 600 (BRAFV600E), which leads to the abnormal activation of MAPK signaling." (PMID 40655947, 2025). "SMM102, a murine melanoma cell line harboring a BRAF mutation, was transplanted into both flanks of C57BL/6 mice, followed by continuous PLX4032 treatment." (PMID 40681872, 2025). "The BRAF mutation, specifically the single point mutation V600E, is one of the most frequently mutated oncogenes in melanoma." (PMID 40981345, 2025). "Based on prevalent mutational patterns, melanoma can be classified into four subtypes: mutant BRAF, mutant RAS, mutant NF1, and Triple-WT (wild type), with BRAF or RAS mutations being the most common drivers of melanoma development." (PMID 40331942, 2025). "FAK/Src signaling has been implicated in the initial adaptive response of BRAF-mutant melanoma cells to BRAFi treatments both in vitro and in vivo, in response to an activated stroma." (PMID 41109929, 2025). "Mutations in the BRAF gene are the most frequent somatic mutations in melanoma, activating specifically the MAPK pathway." (PMID 40941017, 2025).